OR51R1P (olfactory receptor family 51 subfamily R member 1 pseudogene)
Gene: Unitary pseudogene on chromosome 11 (4,418,060 to 4,419,011, forward strand). Ensembl gene ENSG00000237272.
Diseases named in the same sentence as OR51R1P in open-access papers:
OR51R1P is named in the same sentence as 1 disease in open-access papers, as found by Europe PMC text mining. Sharing a sentence is not in itself a finding about the gene and the disease. The quoted sentences say what the papers report.
bacterial meningitis (1 paper, 2024). Inflammation of the membranes surrounding the brain and spinal cord due to a bacterial infection. "In this study, CCR5, KIF5C, OR52P2P, OR52K2, and OR51R1P were co-expression with lncRNA AC091138.1 in bacterial meningitis specific co-expression networks." (PMID 38347610, 2024). "In bacterial meningitis patients, 8 co-expression relationships were constructed between 8 mRNAs (ACBD7, OR52K2, GPR68, SHISA4, KIF5C, OR52P2P, OR51R1P, and CCR5) and 1 lncRNA." (PMID 38347610, 2024).